TYW1B (tRNA-yW synthesizing protein 1 homolog B)
Description:
Involved in the biosynthesis of wybutosine, a hyper modified guanosine with a tricyclic base located at position 37 of eukaryotic phenylalanine tRNA (tRNA(Phe)) that contributes to maintenance of the translational reading frame (By similarity). Catalyzes the condensation of N-methylguanine with 2 carbon atoms from pyruvate to form the tricyclic 4-demethylwyosine, an intermediate in wybutosine biosynthesis (By similarity).
Synonyms: RSAFD2; MGC87315; NCRNA00069; LINC00069
Tractability: PROTAC: ubiquitination databases record sites on it.
Gene: Protein-coding gene on chromosome 7 (72,558,744 to 72,828,260, reverse strand). Ensembl gene ENSG00000277149.
Subcellular location (Human Protein Atlas): Nucleoli; Nucleoli rim; Nucleoplasm
Gene Ontology:
Molecular function: protein binding; 4 iron, 4 sulfur cluster binding; catalytic activity; FMN binding; iron-sulfur cluster binding; tRNA-4-demethylwyosine synthase activity
Biological process: wybutosine biosynthetic process; tRNA processing
Genetic constraint (gnomAD): Loss-of-function variants: 64 observed, 77.68 expected, observed/expected ratio (o/e) 0.82, 90% interval 0.67 to 1.01. The upper end of that interval is the gene's LOEUF score, 1.01, which puts it in group 4 of 6, group 1 being the genes least tolerant of losing a copy. Missense variants: 592 observed, 763.44 expected, observed/expected ratio (o/e) 0.78, 90% interval 0.72 to 0.83. Synonymous variants: 237 observed, 264.69 expected, observed/expected ratio (o/e) 0.9, 90% interval 0.8 to 1.
Homologues: Orthologues: macaque TYW1 (94% identical), chimpanzee TYW1B (92% identical), rat Tyw1 (79% identical), mouse Tyw1 (78% identical), tropical clawed frog tyw1 (69% identical), zebrafish tyw1 (66% identical). Paralogues in human: TYW1 (96% identical).
Diseases named in the same sentence as TYW1B in open-access papers:
TYW1B is named in the same sentence as 4 diseases in open-access papers, as found by Europe PMC text mining. Sharing a sentence is not in itself a finding about the gene and the disease. The quoted sentences say what the papers report.
cardiovascular diseases (1 paper, 2022). "Among these genes, TYW1B, FCER2, SELE, and SDC-1 had some degree of connection with cardiovascular diseases including AF." (PMID 36078037, 2022).
heart disease (1 paper, 2022). "GWAS studies found novel variants of genes including TYW1B that are associated with altered triglyceride levels in heart disease." (PMID 36078037, 2022). "TYW1B is associated with triglyceride metabolism in heart disease." (PMID 36078037, 2022).
TYW1B also shares sentences with these, for which no sentence is quoted: artery disease (1 paper); cancer (1).